IL1B (interleukin 1 beta)
Diseases named in the same sentence as IL1B in open-access papers (continued):
Sharing a sentence is not in itself a finding about the gene and the disease.
Oral ulcer (8 papers, 2020 to 2025). Erosion of the mucous mebrane of the mouth with local excavation of the surface, resulting from the sloughing of inflammatory necrotic tissue. "The levels of inflammatory cytokines IL-6, TNF-α, IL-18, and IL-1β in the oral ulcer group were significantly higher than in the normal group." (PMID 40818135, 2025). "After normalizing saliva for protein content, BD patients with oral ulcers (BD-MA) had significantly higher levels of salivary IL-1β (p=0.01), IL-8 (p=0.02), TNF-α (p=0.004) and IL-6 (p=0.01) than HCs." (PMID 35003055, 2021). "The MPO, SOD, and IL-1β activities were measured in the full-thickness excisional biopsies of oral ulcers." (PMID 33489037, 2020). "Similarly, other preclinical models have shown that PTX significantly reduces the expression of TNFα and IL-1β, thereby promoting the healing of radiotherapy-induced oral ulcers." (PMID 41164763, 2025). "Based on these findings, we hypothesize that altered IL-1β expression levels might similarly influence the pathogenesis of recurrent oral ulcers." (PMID 41560733, 2025). "Therefore, the present study attempted to evaluate the effect of ADSCs seeded onto the curcumin-loaded collagen scaffold on experimental oral ulcers using the histological examination as well as tissue MPO, SOD, and IL-1β assessments." (PMID 33489037, 2020). "Notably, BD patients without oral ulcers (BD-MQ) also had significantly higher salivary IL-1β, IL-8 and TNF-α (p ≤ 0.05) than HCs." (PMID 35003055, 2021). "The elevated saliva cytokines IL-8, IL-1β, and TNF-α in BD patients without oral ulcers could be included in a potential cytokine panel to assist in the differential diagnosis, predicting the reoccurrence of ulcers or systemic relapse, and monitoring treatments." (PMID 35003055, 2021).
orchitis (8 papers, 2019 to 2025). Inflammation of one or both testes due to viral or bacterial infections. "Fibrosis, caspase-3 expression, and accumulations of tumor necrosis factor-α (TNF-α; P < 0.05) and interleukin-1β (IL-1β; P < 0.05), along with an elevated macrophage composition (P < 0.05) characterized the orchitis under HS." (PMID 41402910, 2025). "In this study, the mRNA expressions of IL-2, TNF-α, IL-17A, and IL-1β, which have essential roles in inflammatory processes, were elevated in LPS-induced orchitis; however, PHN have been found to reduce their expression." (PMID 38846786, 2024). "Many studies have also shown that an imbalance between pro- and anti-inflammatory molecules, including TNF-α and IL-1β, in the testes can lead to orchitis." (PMID 38846786, 2024). "IMD can inhibit the gene expression of the proinflammatory cytokines (TNF-α, IL-6, and IL-1β) in LPS-induced rat testis inflammation." (PMID 34434487, 2021). "Previous research shows that the activation of the NLRP3 inflammasome in orchitis promotes the secretion and maturation of IL-1β and, thus, decreases male fertility." (PMID 33193351, 2020). "Overall, CaSR plays an important role in the proinflammatory process of UPEC-induced orchitis by promoting the secretion of IL-1β in TM." (PMID 33193351, 2020). "We find that CaSR promotes the secretion of proinflammatory factor IL-1β in the NLRP3 inflammatory corpuscle pathway in orchitis and that CaSR inhibitors reduce inflammatory damage to spermatogenic epithelial cells." (PMID 33193351, 2020). "Several studies have suggested that macrophages and IL-1β are involved in the initiation and progress of orchitis." (PMID 31474981, 2019). "Overall, PK2 plays important roles in the pro-inflammatory process of UPEC-induced orchitis by promoting IL-1β secretion in TM." (PMID 31474981, 2019). "Considering the potential relationship between PK2 and IL-1β, we inferred that PK2 is closely associated with the regulation of the inflammatory process during UPEC-induced orchitis." (PMID 31474981, 2019). "In addition, exosomes isolated using a mouse model of UPEC-induced orchitis promoted macrophage M1 activation and consequently increased the levels of proinflammatory cytokines (e.g., TNFα, IL-1β, and IL-6) in the testes." (PMID 38190378, 2024). "Animals subjected to LPS were found to have severe orchitis, as evidenced by increased oxidative stress and surging inflammatory mediators (TNF-α, IL-1β, and IL-6), with declined IL-10 levels." (PMID 39845795, 2024). "Orchitis may be induced by discrepancies in the inflammatory and anti-inflammatory cytokine levels in testicular cells, including TNF-α, interleukin (IL)-1β, (IL-6), and IL-10." (PMID 39845795, 2024). "Lipopolysaccharides (LPS) is a key element of the external membrane found in Gram-negative bacteria and can cause orchitis by promoting the production of ROS and inflammatory mediators such as TNF-α, IL-6, and IL-1β in testicular tissue." (PMID 39845795, 2024). "Despite that NLRP3 and inflammation-related IL-1β are upregulated in UPEC-infected TM, whether CaSR induces NLRP3 inflammasome activity in the pathogenesis of orchitis is unclear." (PMID 33193351, 2020).
osteonecrosis (8 papers, 2017 to 2026). A none disease characterized by death of bone tissue due to a lack of blood supply. "Metformin's effect was demonstrated by fewer number of empty osteocyte lacunae, a hallmark of osteonecrosis, fewer apoptotic osteoclasts, and suppression of inflammatory mechanisms, including macrophage infiltration (F4/80) and IL‐1β production." (PMID 41346233, 2026). "Interestingly, Vicari and colleagues reported increased risk of osteonecrosis among SCD patients carrying IL-1β +3954C > T SNP." (PMID 31205626, 2019). "We also demonstrated that NONFH is a chronic inflammatory disease involving persistent enrichment with IL-6 and IL-1β, osteonecrosis and fibrosis in the local lesion." (PMID 35573242, 2022). "Furthermore, another study also indicated that oral administration of Ok-PDRN inhibited the expression of IL-1β, matrix metalloproteinase (MMP)-3, and MMP-7, as well as production of inflammatory mediators including COX-2, prostaglandin E2 (PGE2), and TNF-α in an MIA-induced osteonecrosis model." (PMID 34067499, 2021).
periodic fever syndrome (8 papers, 2012 to 2025). Fevers of unknown etiology recurring over months or years. "We studied the potential contribution of disordered mitochondrial biology in to IL-1β mediated inflammation in the human monogenetic periodic fever disorder, mevalonate kinase deficiency (MKD), which gives rise to the hyper-IgD and periodic fever syndrome." (PMID 24356959, 2014). "In most periodic fever syndromes, the generalized inflammation is driven by IL-1β generated through proteolytic cleavage by the NLRP3 inflammasome." (PMID 24356959, 2014). "Most hereditary periodic fever syndromes are mediated by deregulated IL-1β secretion." (PMID 24356959, 2014). "Similarly, IL-1β, but not IL-1α, is the etiologic agent of hereditary periodic fever syndromes and other “autoinflammatory” diseases in humans." (PMID 23056330, 2012).
Pleural effusion (8 papers, 2008 to 2024). The presence of an excessive amount of fluid in the pleural cavity. "In this study, we also evaluated the availability of 12 serum cytokines within 48 h of symptom onset to predict AP patients with pleural effusion, and IL‐1β, IL‐6, IL‐8, and IL‐10 all showed good predictive value." (PMID 38411379, 2024). "Previous research indicated that the levels of IL-1β were lower in the pleural effusions of tuberculous pleurisy than empyema." (PMID 27034588, 2016). "The levels of PAI-1, IL-1β were higher and t-PA, IL-6 were lower in pleural effusions of the patients with tuberculous empyema and who must undergo operation than the patients who could be treated with closed drainage and anti-TB chemotheraphy." (PMID 27034588, 2016). "In addition, a trend towards significance was found for association of the NF-κB pathway related genes IL1B and NFKB1 with the occurrence of severe complications and for IL8 and NFKB2 with pleural effusion." (PMID 18398488, 2008). "Moreover, our results also indicated that the IL-1β levels of pleural effusions of the patients with tuberculous empyema and who must undergo operation were higher than the patients who could be treated with closed drainage and anti-TB chemotheraphy." (PMID 27034588, 2016). "The IL‐8, IL‐1β, sIL‐2R, WBC, CRP, PCT, SAA, ESR, ALT, ferritin, FIB and pleural effusion were excluded from the analysis due to their high non‐response rate." (PMID 37142438, 2023). "In the pleural effusion of mice receiving intrapleural injection, the levels of TNF-α (P = 0.0004) and IL-1β (P = 0.0422) were significantly higher than those of the NS group." (PMID 34966384, 2021). "One possible explanation for this finding is that the IL-1β levels in PTB vs. TP patients are easier to measure in the plasma, compared with pleural effusions, respectively." (PMID 26881918, 2016). "This study has showed that the levels of IL-1β, PAI-1, and t-PA in the pleural effusions were different between tuberculous pleurisy and tuberculous empyema; it could be helpful to differentiate the two diseases." (PMID 27034588, 2016). "The levels of IL-1β, PAI-1, and t-PA in the pleural effusions were different between tuberculous pleurisy and tuberculous empyema; it could be helpful to differentiate the two diseases." (PMID 27034588, 2016). "The aim is to examine whether the interleukin-1β (IL-1β), IL-2, IL-6, tumor necrosis factor-α (TNF-α), plasminogen activator inhibitor type-1 (PAI-1), and tissue plasminogen activator (t-PA) levels were different in pleural effusions of tuberculous pleurisy and tuberculous empyema." (PMID 27034588, 2016). "We aimed to examine whether the interleukin-1β (IL-1β), IL-2, IL-6, tumor necrosis factor-α (TNF-α), plasminogen activator inhibitor type-1 (PAI-1), and tissue plasminogen activator (t-PA) levels were different in pleural effusions of tuberculous pleurisy and tuberculous empyema." (PMID 27034588, 2016). "According to receiver operating characteristic curve analysis, the four cytokines (MIF, MIP-3α, IL-1β, and ENA-78) had areas under the curve (AUCs) greater than 0.710 for discriminating parapneumonic pleural effusion from noninfectious pleural effusions." (PMID 33469074, 2021).
primary biliary cholangitis (8 papers, 2017 to 2025). Primary biliary cholangitis (PBC) is a chronic and slowly progressive cholestatic liver disease of autoimmune etiology characterized by injury of the intrahepatic bile ducts that may eventually lead to liver failure. "For example, a study in patients with primary biliary cirrhosis revealed the increased levels of IL-1β, IL-6, and TNF-α in such patients compared to healthy controls." (PMID 28299346, 2017). "Indeed, elevated circulating levels of both IL-1β and IL-1Ra are detected in the serum of patients with chronic liver diseases, including alcoholic liver disease, chronic hepatitis B and C, and primary biliary cirrhosis." (PMID 30875826, 2019). "In Novosphingobium aromaticivorans-induced primary biliary cholangitis (PBC), Galectin-3 was found to enhance NLRP3 inflammasome activation, thereby stimulating IL-1β production and worsening the progression of PBC." (PMID 37685870, 2023). "In primary biliary cholangitis (PBC), hepatic expression of SOCS1 is inhibited by microRNA-155, which may result in the increased production of proinflammatory cytokines such as tumor necrosis factor α (TNFα) and interleukin 1β (IL-1β)." (PMID 31717271, 2019).
pyoderma gangrenosum (8 papers, 2015 to 2025). An idiopathic, rapidly evolving, and severely debilitating disease occurring most commonly in association with chronic ulcerative colitis. "Pathophysiologically, pyoderma gangrenosum is an autoinflammatory neutrophilic dermatosis marked by innate immune dysregulation, neutrophil hyperactivation, and overexpression of cytokines such as TNF-α, IL-1β, IL-17, and IL-23." (PMID 41440229, 2025).
Senile plaques (8 papers, 2014 to 2022). Senile plaques are extracellular deposits of amyloid in the gray matter of the brain. "IL-1β also enhances the synthesis of Aβ protein precursor mRNA in human endothelial cells suggesting that IL-1β also influences the formation of senile plaques." (PMID 35813949, 2022). "IL1A, IL1B, IL2, IL8, IFNγ, and TNFα have been found to be associated with senile plaques." (PMID 25197660, 2014). "One with high expression levels of IL-1β, TNF-α and IL-12A typical of a pro-inflammatory phenotype related with oligomeric Aβ, the other located near senile plaques with upregulation of IL-1ra, Arginase 1 and FIZZ, is characteristic of a reparative phenotype." (PMID 35011699, 2022). "In the brains of AD patients, microglial activation is observed in the vicinity of senile plaques at all stages of the disease and is accompanied by increased levels of proinflammatory molecules (e.g., TNF, IL-1β, IL-6, prostaglandins)." (PMID 34228639, 2021). "Rt (10 μg/ml) significantly inhibited the mean protein level of interleukin-1β (IL-1β) in the organotypic hippocampal slice cultures following treatment with chromogranin A (CGA, 10 nM) and pancreastatin (10 nM), endogenous microglial activators present in senile plaques." (PMID 29854069, 2018).
shigellosis (8 papers, 2011 to 2024). Shigellosis is a bacterial infection leading to dysentery and is caused by Shigella, which are small, ubiquitous Gram-negative bacteria belonging to the enterobacteria family. "CXCL1 and IL-1β are NF-κB-induced cytokines previously implicated in driving disease during shigellosis by initiating inflammation and promoting innate immune cell recruitment to the gut." (PMID 36645406, 2023). "Hence, it was of interest to investigate the relationship between host (mucin) and pathogen interaction, including Shigella induced expression of MUC2 and IL-1β during shigellosis." (PMID 22073249, 2011). "Despite these differences, there was no strong correlation between IL-1β levels or fecal blood score and Casp11 genotype, suggesting that while Casp11 contributes to resistance, there are additional genetic modifiers present on the 129 or B6 background that affect susceptibility to shigellosis." (PMID 36645406, 2023). "In both animal models, S. flexneri induces the expression of proinflammatory cytokines, including IL-1β and TNF-α, as observed in humans suffering from shigellosis." (PMID 28650995, 2017). "The p-values were significant (<0.05) for IL-1β, IL-10, IFN-γ and TNF-α, but IL-2 and IL-4 levels were insignificant in shigellosis patients’ sera." (PMID 28767653, 2017).
streptococcal infection (8 papers, 2015 to 2024). Any of the several infectious disorders caused by members of streptococcus, a genus of gram positive bacteria belonging to the family Streptococcaceae. "IL-1β signaling is involved in the immune response to multiple species of streptococci, and IL-1β-deficient mice are more susceptible to streptococcal infections." (PMID 37352427, 2023). "Our results suggested that after streptococcal infection, B cells and other immune cells were activated by IL-1β to protect the organisms from pathogenic stress, exerting a role in modulating the cellular immune response." (PMID 35309129, 2022). "In a mouse model of sub-cutaneous Streptococcus infection, IL-1α was shown to induce unique transcriptomic changes to the liver, whilst IL-1β had more effect on the spleen transcriptome." (PMID 39127259, 2024). "IL-1α probably plays at most a minor role during streptococcal infections, as IL-1β−/− mice phenocopy IL-1R−/− mice in their resistance to GBS." (PMID 26500655, 2015). "However, there are very likely additional mechanisms allowing for IL-1β activation during streptococcal infection, either by alternative inflammasome or by inflammasome-independent mechanisms." (PMID 26500655, 2015). "Individually, IL-1β, TNF-β, and zymography showed differences between streptococcal infections and all other patients, yet only an RF-based model revealed their full diagnostic potential with an AUC of 0.969." (PMID 28318629, 2017). "In this context, Vγ9/Vδ2 T cells and TNF-α appear to be particularly relevant in Gram-negative infections, IL-1β and MMPs in streptococcal infections, and IL-16 and sIL-6R in CNS infections." (PMID 28318629, 2017). "Although NLRP3 and AIM2 participate in IL-1β release by bmDCs and MΦ following infection by GBS and S. pneumoniae, the implication of NLRP1 and NLRC4 have not yet been described following streptococcal infection." (PMID 31262357, 2019).
Streptococcus pneumonia (8 papers, 2018 to 2024). "Our results demonstrate that HMPV uses a TBK1- IFN-β-IFNAR-driven mechanism to differentially control transcription of specific cytokines and reduce IL-1β transcription in response to LPS or heat-killed Pseudomonas aeruginosa and Streptococcus pneumonia." (PMID 37435074, 2023). "HMPV strongly suppresses IL-1β transcription in response to LPS or heat-killed Pseudomonas aeruginosa and Streptococcus pneumonia, while enhancing mRNA levels of IL-6, TNF-α and IFN-β." (PMID 37435074, 2023). "Although the biology of NLRP3 has been widely studied in macrophages and dendritic cells, studies have shown that neutrophils are the main source of the NLRP3-dependent IL-1β production in Staphylococcus aureus and Streptococcus pneumoniae mouse infections." (PMID 33440601, 2021). "Xin-Yi-Qing-Fei-Tang can reduce the nasal colonization of Streptococcus pneumonia, which causes sinusitis and increases tumor necrosis factor-alpha (TNF-α), interleukin-1 beta (IL-1β), interleukin-6 (IL-6), and monocyte chemotactic protein-1 (MCP-1) levels and the migration of macrophages." (PMID 33204289, 2020). "We previously demonstrated that maturation and secretion of IL-1β require activation of AIM2 and NLRP3 inflammasome in Streptococcus pneumonia-infected macrophages and neutrophils." (PMID 34017331, 2021). "However, some research reported that IL-1β secretion was independent of activation of TLR4 in Streptococcus pneumonia and Streptococcus suis-infected cells in vitro." (PMID 34017331, 2021).